ERBB4 (erb-b2 receptor tyrosine kinase 4)
Diseases named in the same sentence as ERBB4 in open-access papers (continued):
Sharing a sentence is not in itself a finding about the gene and the disease.
lung carcinoma (51 papers, 2014 to 2026). "At the same time, particularly in lung cancer, mutations in ErbB4 have been identified." (PMID 38017514, 2023). "ERBB4-mediated nuclear signaling, which is associated with cancer development, was upregulated in Black samples compared to White samples in breast, colorectal, kidney renal clear cell, and lung carcinomas." (PMID 37345032, 2023). "As a result, ERBB4 mutations may be a novel biomarker for lung cancer immunotherapy." (PMID 34620079, 2021). "explored the mechanisms of miR-193a-5p in regulating lung cancer metastasis by downregulating the ERBB4/PIK3R3/mTOR/S6K2 signaling pathway." (PMID 40230863, 2025). "The EGF receptor (EGFR) family consists of four transmembrane receptors, which include EGFR (HER1/erbB-1), HER2 (erbB-2/neu), HER3 (erbB-3), and HER4 (erbB-4); and is commonly overexpressed in lung cancer." (PMID 39218855, 2024). "In lung cancer, ErbB4 is overexpressed, and its localization is transferred from the cell membrane and cytoplasm to the nucleus and cytoplasm." (PMID 37800117, 2023). "Other frequently mutated genes in the tumor tissue samples used in our lung cancer study were FLT3 (altered in 87% of the samples), KDR (84%), CSF1R (72%), PIK3CA (59%), and ERBB4 (53%)." (PMID 35330454, 2022). "Rearrangements of MET and the ErbB family RTKs (EGFR, ERBB2, ERBB3, and ERBB4) in lung cancer are less well documented and mostly as case reports." (PMID 36369474, 2022). "For instance, in related studies super-enhancer-regulated lncRNA UCA1 has been found to serve as an endogenous competitive RNA binding miR-193a-3p to regulate ERBB4, thereby promoting proliferation and colony formation of lung cancer cells." (PMID 35663324, 2022). "Our results showed that Wogonin resulted in reduced expression of ERBB4, thus preventing the invasion and metastasis of ERBB4-mediated lung cancer cells." (PMID 34630106, 2021). "Moreover, certain ERBB4 polymorphisms (SNPs rs6742399, rs6740117, and rs6747637) are firmly linked to a higher risk of lung cancer, suggesting that ERBB4 mutation might predispose to the development of lung cancer." (PMID 34620079, 2021). "The ERBB4 mRNA level was higher in the breast and colorectal cancer tissues and observably lower in the bladder, brain and CNS, head and neck, kidney, and lung cancers compared with the corresponding normal tissues." (PMID 33732282, 2021). "Regarding lung cancer, the up regulation of a potent oncogene, ERBB4, generated by UCA1 was achieved by binding miR-193-3p." (PMID 33422052, 2021). "ErbB4 expression in lung cancer cells was significantly decreased upon treatment with Wogonin in a dose-dependent manner (p < 0.05)." (PMID 34630106, 2021). "The HER family is composed of four members, including EGFR/HER1/ErbB1, HER2/ErbB2, HER3/ErbB3, and HER4/ErbB4, and plays a key role in the pathogenesis of various human solid tumors, including breast, gastric and lung cancers." (PMID 29233126, 2017). "Further highlighting the importance of this axis in cancer, two recent studies have reported both tumor and metastasis suppressive functions for the miR-193b paralog miR-193a in lung cancer, through downregulation of ErbB4." (PMID 28542597, 2017). "Their findings were supported by another recent study that confirmed that miR-193a-3p directly targets ERBB4 in lung cancer." (PMID 29115941, 2017). "MicroRNA-193a-3p and −5p function as tumour suppressors and inhibit the metastasis of lung cancer by down-regulating the ERBB4/PIK3R3/mTOR/S6K2 signalling pathway." (PMID 26395400, 2015).
lung carcinoma (continued). "Furthermore, the S303F mutation, together with a previously identified activating ERBB4 mutation, E715K, promoted resistance to third-generation EGFR inhibitor osimertinib in EGFR-mutant lung cancer model in vitro and in vivo." (PMID 41437739, 2025). "Human lung cancer cell lines (A549) were treated with wogonin (0, 5, 15, or 20 μmol/L), and it was found that wogonin significantly improved caspase‐3, downregulated Bcl‐2, and reduced ErbB4 expression." (PMID 41164269, 2025). "ErbB4 is overexpressed in a variety of epithelial tissue-derived malignancies, such as lung cancer, ovarian cancer, prostate cancer, bladder cancer, and cervical cancer, which suggests that the change of ErbB4 expression is closely related to the occurrence and evolution of tumors." (PMID 37800117, 2023). "The overexpression of ErbB4 may be related to lung cancer lymph node metastasis, tumor node metastasis staging, and postoperative survival rate." (PMID 37800117, 2023). "ERBB4 mutations were found in gastric carcinomas, albeit to a lesser extent than in colorectal and lung carcinomas, however, to our knowledge, notable SNVs have not been reported in Lymph-CLL." (PMID 35054395, 2021). "ErbB4 expression also significantly decreased in lung cancer cells after treatment with Wogonin." (PMID 34630106, 2021). "Wogonin may also inhibit the expression of ErbB4, thus affecting the downstream signaling pathway and inhibiting the invasion and metastasis of lung cancer cells." (PMID 34630106, 2021). "Among validated targets for this microRNA, the PTEN gene was associated in gastric cancer and renal cell carcinoma and ERBB4 in lung cancer, suggesting that regulation by miR-193 could act as a tumor suppressor." (PMID 33461524, 2021). "We looked at the distribution of breakpoints in ALK, RET, ROS1, NTRK1, as well as other kinase genes known to generate oncogenic fusions in lung cancer, such as EGFR, ERBB4, MET, FGFR3, and EPHA245." (PMID 38877018, 2024). "The DEGs centrally had direct interaction with EGFR, ERBB2, ERBB4, MET and TUBB, which suggested that the divergence between the primary CRC and the metastases of CRC was related to lung cancer." (PMID 30642283, 2019). "miR-193a can also act as a tumor suppressor by targeting ERBB4 (human EGFR 2, HER2) and play a role in inhibiting proliferation and invasion and accelerating the apoptosis of lung cancer cells." (PMID 29016617, 2017). "ProKinO, an ontology tool for searching cancer kinome databases, has also identified various cancer-associated C-spine mutations, such as a valine to phenylalanine substitution in the receptor tyrosine kinase ErbB4 (V732F) and in the serine/threonine kinase BRAF (V471F) in lung carcinoma." (PMID 41207627, 2025). "We found that compared to recurrence patients, Met, ALK, APC, PTEN, ERBB4, NF1, and other genes in recurrence-free patients never mutated, involving multiple tumor suppressor genes and lung cancer-driven genes." (PMID 31182981, 2019). "MMP-7 overexpression could also regulate the proliferation of lung cancers through activation of EGFR and the production of mature HB-EGF to activate the receptor ErbB4." (PMID 25588786, 2015). "Furthermore, Met, ALK, APC, PTEN, ERBB4, NF1, and other genes, involving multiple tumor suppressor genes and lung cancer-driven genes, did not mutate in recurrence-free patients when compared with recurrent patients." (PMID 31182981, 2019). "However, this percentage could increase to 71.43%, considering that ESR1 (2.86%), ERBB4 (2.86%), and PIK3CA (8.57%) are not actionable genes in lung cancer." (PMID 39769478, 2024).
gastric cancer (44 papers, 2011 to 2025). A primary or metastatic malignant neoplasm involving the stomach. "It has been shown that, over expression of ErbB1 and ErbB3, and ErbB4 proteins were significantly associated with poor prognosis in gastric cancer patients." (PMID 30621788, 2019). "The druggable gene ERBB4 was also reported to be mutated in malignant ascites of patients with gastric cancer." (PMID 27270314, 2016). "Meanwhile, overexpression of ErbB1 has been correlated with gastric cancer, human hepatocellular carcinoma, and oesophageal cancer, and ErbB3 has been implicated in breast, bladder, and gastric cancers, whereas ErbB4 is also commonly associated with gastrointestinal cancer." (PMID 35800225, 2022). "While therapeutic strategies targeting other ERBB receptors (e.g., HER2/ERBB2) have shown success in treating breast and gastric cancers, ERBB4 remains relatively underexplored." (PMID 40806544, 2025). "A study of gastric cancer patients detected a high frequency of mutations in MLL4, ERBB3, FBXW7, MLL3, mtor(RPTOR), NOTCH1, PIK3CA, KRAS, ERBB4 and EGFR." (PMID 33909629, 2021). "Soluble forms of TMEFF2 extracellulardomain have been reported to weakly stimulate erbB-4/HER4 tyrosine phosphorylationin MKN 28 gastric cancer cells, and promote survival of mesencephalic dopaminergicneurons in primary culture." (PMID 21559523, 2011). "Allicin targets the miR-383/ERBB4 axis to inhibit the invasion of gastric cancer." (PMID 37663388, 2023). "In the present study, we identified three frequently amplified genes from 30 candidate genes using real-time quantitative PCR method, including ERBB4, C-MET and CD44, and further explored their association with clinicopathological characteristics and poor survival in a cohort of gastric cancers." (PMID 22606006, 2012). "Because highly frequent amplification of ERBB4, C-MET and CD44 was demonstrated in gastric cancer, their association with clinicopathological characteristics was analyzed in a cohort of clinically well-characterized gastric cancers." (PMID 22606006, 2012). "Notably, our data showed that amplification of ERBB4 and CD44 was significantly associated with poor prognosis in gastric cancer, is new to the literature." (PMID 22606006, 2012). "The group with SOX2 suppression had higher rates of mutations in many gastric cancer-associated genes such as epigenetic modifiers ARID1A, KMT2D, KMT2C, and KMT2B, as well as higher rates of mutations in genes encoding for receptor tyrosine kinases ERBB4 and FGFR1." (PMID 40149431, 2025). "In addition, ERBB4 is reportedly associated with EMT in lung and gastric cancer cells." (PMID 35130915, 2022). "By contrast, miR551b-3p expression levels were found to be inversely correlated with the prognosis of gastric cancer (GC) as a result of inhibiting ERBB4 expression." (PMID 31137914, 2019). "The presence of neuromodulin, a ligand for ErbB3, leads to heterodimerization of ErbB2, ErbB3, and ErbB4, thereby reducing the cytotoxicity of T-DMI in gastric cancer cell lines." (PMID 37305567, 2023). "ERBB4 apparently is involved in phosphorylation of PI3K and Akt and promotes proliferation of gastric cancer cells." (PMID 35072776, 2022). "Multiple oncogenic signaling pathways (gastrin-CREB, NGF-neurotrophin, PDGF, EGFR, ERK, ERBB4, FGFR1, RAS, VEGFR2 and RAF/MAP kinase) known to be active in aggressive gastric cancers were strikingly diminished in gastric cancers with low DOK6 expression." (PMID 29872697, 2017). "These mapped with high statistical significance to ten canonical signaling pathways, all of which were less active in low DOK6 gastric cancers: gastrin-CREB, NGF, PDGF, EGFR, ERKs, ERBB4, FGFR2, RAS, VEGFR2 and RAF/MAP kinase." (PMID 29872697, 2017). "Amplification of ERBB4, C-MET and CD44 significantly affected the poor survival of gastric cancer patients." (PMID 22606006, 2012).
gastric cancer (continued). "Overexpression of ERBB4 was found to be closely related to poor outcomes and advanced tumor states and inhibiting the expression of ERBB4 via the PI3K/Akt signaling pathway reduced the proliferation of gastric cancer cells." (PMID 34925436, 2021). "Although there is not any report of ErbB3 or ErbB4 overexpression in gastric cancer, ErbB3 expression is frequently seen in advanced stages of gastric cancers and is correlated with poor prognosis." (PMID 30621788, 2019). "Subsequently, we used the same method to analyze the copy number of ERBB4, C-MET and CD44 genes in the 128 gastric cancers and 37 normal controls." (PMID 22606006, 2012). "With a gene copy number of 4 or more defined as gene amplification, we found that ERBB4, C-MET and CD44 genes were frequently amplified in gastric cancers, however, other genes were not or infrequently amplified in gastric cancers, ranging from 0 to 8% (data not shown)." (PMID 22606006, 2012).
glioma (34 papers, 2014 to 2025). A benign or malignant brain and spinal cord tumor that arises from glial cells (astrocytes, oligodendrocytes, ependymal cells). "The effects of circ_0001162 on glioma cells were also associated with the positive regulation of ERBB4." (PMID 34057019, 2021). "An additional analysis of ERBB4 loss in glioma cell lines was later explored in the HGCC gliomasphere database." (PMID 29342193, 2018). "The results of co-transfection with si-circ_0001162+ ERBB4 in LN18 cells and circ_0001162+ si-ERBB4 in A172 cells further validated that the effects of circ_0001162 on glioma cell proliferation, migration and invasion were associated with the positive regulation of ERBB4." (PMID 34057019, 2021). "The discovery of the circ_0001162/miR-936/ERBB4 network might provide a ponderable insight into the underlying biological peculiarity of glioma." (PMID 34057019, 2021). "Data from the Cancer Cell Line Encyclopedia (CCLE) suggests copy number loss of ERBB4 may be significant in glioma." (PMID 29342193, 2018). "However, different levels of ERBB4 expression are only associated with survival in all glioma cases, but fail to show statistical significance among glioma subclass astrocytoma cases." (PMID 26614510, 2016). "Whereafter, our rescued experiments manifested that ERBB4 protein downregulation was induced by miR-936 mimic and expression promotion was caused by miR-936 inhibitor, whereas these effects were alleviated after ERBB4 up-regulation and under-expression, respectively, in glioma cells." (PMID 34057019, 2021). "Circ_0001588 upregulates ERBB4 to promote glioma malignant progression through sponging miR-128, while circ_0001162 enhances cell proliferation and invasion of glioma through the miR-936/ERBB4 axis." (PMID 38200584, 2024). "Constitutive ERBB4 tissue expression is variable but is known to be altered in human cancers including carcinomas, gliomas, and sarcomas." (PMID 37855863, 2024). "ERBB4 protein is a tyrosine protein kinase and a member of the epidermal growth factor receptor subfamily, which will promote the pathogenesis of glioma." (PMID 37576896, 2023). "Circ_0074026 upregulated the ERBB4 level by absorbing miR-1304, thereby promoting carcinogenesis in glioma cells." (PMID 37020694, 2023). "This circular RNA targets miRNA-1304, which appears to modulate ERBB4 expression and possibly contribute to glioma progression." (PMID 36119496, 2022). "The role of the different ErbB4 isotypes in high grade gliomas is still unclear and future research will hopefully shed some light on this question." (PMID 36119496, 2022). "In 2019, Chen and colleagues reported a novel regulatory pathway involving ErbB4 and circular RNA, which is upregulated in glioma (GM) cells." (PMID 36119496, 2022). "For example, in addition to regulating tumor resistance by sponging miR-329-3p, circPITX1 can also regulate ERBB4 expression by sponging miR-1304, thus promoting glioma progression." (PMID 36358938, 2022). "This study proved that circ_0001162 accelerated the tumorigenesis of glioma via the mediation of the miR-936/ERBB4 axis, providing a novel regulatory network about the pathological mechanism of glioma with circ_0001162 as an object of study." (PMID 34057019, 2021). "The aim of this study was to investigate the regulatory network among circ_0001162, miR-936 and ERBB4 in regulating the initiation and development of glioma." (PMID 34057019, 2021). "The expression of ERBB3 and ERBB4 mRNA in gliomas was notably negatively correlated with the level of B cell infiltration (ERBB3, r = − 0.08882, p < 0.0201, ERBB4, r = − 0.1591, p < 0.001)." (PMID 33892666, 2021). "Mechanically, they proposed that circPITX1 regulates ERBB4 expression to promote glioma progression by sponging miR-1304." (PMID 33995499, 2021). "EGFR and ERBB2 were notably downregulated in IDH mutant gliomas, while ERBB3 and ERBB4 were upregulated, which was associated with a poor prognosis." (PMID 33892666, 2021).